KDM3A (lysine demethylase 3A)
Diseases named in the same sentence as KDM3A in open-access papers (continued):
Sharing a sentence is not in itself a finding about the gene and the disease.
cancer (continued). "In conclusion, the KDM3A/METTL16/PDK1 axis plays an important role in cancer development and TKI resistance, which may offer new prognostic biomarkers and therapeutic targets for TKI resistance in the future." (PMID 42004224, 2025). "KDM3A overexpression is unique among the KDM3 subfamily in cancer, conferring colony formation, migration, invasion, and metastasis through Hippo and YAP1 pathway upregulation Glycolytic genes and glucose transport genes, such as GLUT3/SLCA3, are directly activated by KDM3A and HIF1." (PMID 39299930, 2024). "These distinct roles of KDM3A in different cancer types may be attributed to different signaling mechanisms, which necessitates further investigation." (PMID 38165573, 2024). "Among the KDM3 proteins, KDM3A has been largely studied in cancers." (PMID 38926399, 2024). "In addition, two methylated modifications (H3K9 me2 and me3) of the DNA packaging protein histone H3 decrease during cancer transformation, and the demethylase KDM3A/JMJD1A gradually increases." (PMID 38169859, 2023). "Specifically, scoring and predictions are provided for peptides comprising the KDM3A interactome to identify potential substrates that could facilitate the role of KDM3A in cancer." (PMID 35625569, 2022). "Moreover, we accessed the KIRC TCGA RNAseq dataset and confirmed that the expression of KDM3A was significantly higher in cancer tissues than in cancer-adjacent normal tissues." (PMID 33888871, 2022). "Thus, we show that KDM3A is not only a direct downstream target of miR-335, but also a compelling drug target due to its regulatory roles in cancer progression." (PMID 33888871, 2022). "As a direct downstream target, KDM3A may potentially contribute to cancer growth and metastasis, due to regulation by miR-335." (PMID 33888871, 2022). "In a previous study, KDM3A- mediated transactivation of ETS1 was shown to occur via the H3K9me2 decrease in the genomic region flanking the promoter and was especially linked to cancer development." (PMID 35338235, 2022). "Mechanistically, KDM3A could induce the production of inhibitory cytokines in lung adenocarcinoma cells, thereby promoting immune escape of cancer cells." (PMID 34044859, 2021). "To examine whether DHA exhibited anti-cancer activity via regulating the expression of KDM3A, we used RT-qPCR and western blot assays to determin the KDM3A expression levels in T24 cells after treatment with DHA for 24 h." (PMID 31956358, 2020). "In this review, we focus on recent studies highlighting the oncogenic functions of KDM3A in cancer." (PMID 32354028, 2020). "Moreover, KDM3A and Ets1 also positively control a group of genes commonly overexpressed in pediatric cancers relative to normal tissues (‘Whiteford Pediatric Cancer Markers’)." (PMID 32697014, 2020). "Thus, KDM3A is a compelling drug target because of its regulatory roles in chromatin organization and relevance to diseases including cancer." (PMID 32354028, 2020). "The KDM3A and Ets1 upregulated transcriptomes, alone and together, also contain numerous additional genes implicated in cancer promotion, which are not dependent on PAX3/FOXO1 for expression." (PMID 32697014, 2020). "Consequently, further studies are essential to discover promising inhibitors that can selectively inhibit specific KDMs including KDM3A in the vision of treating diseases not limited to cancers." (PMID 32354028, 2020). "In addition to AR and HIF-1α, c-Myc is posttranscriptionally controlled by KDM3A, leading to cancer proliferation and survival." (PMID 32354028, 2020). "Considering the proposed co-regulatory relationship between KDM3A, KDM4B, and FOXA1, which facilitates a cancer phenotype in ER-positive BC, these data together suggest that targeting KDM3A and KDM4B simultaneously may be an efficacious therapeutic strategy." (PMID 31390833, 2019).
cancer (continued). "Through the catalytic removal of mono- and N-dimethyl groups from lysine 9 of histone H3, KDM3A acts as a transcriptional activator of multiple genes involved in spermatogenesis, fat storage, and energy expenditure as well as of diverse types of cancers." (PMID 28246120, 2017). "The different role of Kdm3a in different types of cancer may be attributed to the cell type-specific gene expression profiles regulated by Kdm3a." (PMID 29156681, 2017). "The specific roles of KDM3A in the pathogenesis of cancers are now being delineated." (PMID 26728187, 2016). "As previously discussed, we have shown a potential cancer specific growth-inhibitory phenotype upon KDM3A depletion, indicating targeting KDM3A may be a useful cancer specific treatment." (PMID 25488809, 2015). "KDM3A depletion has previously been shown to reduce cell growth in a number of cancer contexts." (PMID 25488809, 2015). "Activation of KDM3A leads to the loss of H3K9 repressive mark, facilitating the transcriptional activation of target genes involved in various physiological and pathological processes including spermatogenesis, mammalian sex determination, lipid metabolism and cancer development." (PMID 40033066, 2025). "Moreover, increasing evidence has indicated the key roles of KDM3A in promoting cancer progression." (PMID 32354028, 2020). "Interestingly, the level of KDM3A is relatively similar in different stages and grades of cancer." (PMID 32354028, 2020). "Although the brunt of the current focus of overexpression of KDM3A in various types of cancer has been on its transcriptional targets, our work suggests that cytoplasmic KDM3A may act as an important cytoskeletal rheostat integrating mechanosensation with cell adhesion and signaling through cilia." (PMID 28246120, 2017). "To further investigate the role of KDM3A/JMJD1A in regulating transformation, we knocked it down in HMC-LTR using small interfering RNA (siRNA) and found that KDM3A/JMJD1A deficiency rescued the expression of most cancer-related genes in HMC-LTR to the levels in primary cells." (PMID 27034728, 2016). "This is significant as it demonstrates that KDM3A is an E2-independent regulator of ER signalling in endocrine therapy-resistant disease, and therefore may be a useful treatment to abrogate ER signalling in these cancer types." (PMID 25488809, 2015). "BRG1, the ATPase subunit of the BAF chromatin remodeling complex, has been shown to cooperate with KDM3A and ETS1 on chromatin, and to promote invasive and metastatic properties in other cancers." (PMID 39448867, 2025). "Integration with our previous transcriptome data for KDM3A and ETS1 in the same cell lines confirmed regulatory control of genes related to cancer growth and metastasis." (PMID 39448867, 2025). "In this study, we detected the KDM3A gene in MCF-10 A and MDA-MB-231 specimens, as this gene is significantly upregulated in cancer and correlates with poor prognosis in BC patients." (PMID 38165573, 2024). "Simultaneous knockdown of KDM3A and KDM3B reduced the tumorigenic potential of cancer stem-like cells in CRC cells through regulation of the Wnt/β-catenin pathway." (PMID 38926399, 2024). "Suppression of H3K9me2/me3 demethylase activity such as KDM3A (JMJD1A), KDM4C (JMJD2C), and KDM7C (PHF2) in tissue specific stem cell cultures and cancer cells can lead to premature senescence, increased DNA damage and genomic instability." (PMID 34017357, 2021). "Overall, our results indicate that hypoxia induces KDM3A overexpression, conferring growth advantage to ESCC submitted to IR, highlighting its role in cancer progression and therapy resistance." (PMID 33318475, 2020). "KDM3A has exhibited ability to transcriptionally increase the expression of HOXA1 by erasing the H3K9me2, thus promoting the cell cycle progression in cancer cells." (PMID 33520978, 2020).
cancer (continued). "KDM3A and KDM3B are well known to be tightly related to cancer, whereas KDM3C and KDM4D are relatively unstudied in cancer development." (PMID 32354028, 2020). "Furthermore, published reports regarding KDM3A has shown its effect on proliferation, migration, invasion, progression and prognosis 29-32, which suggested that KDM3A may be an important marker of cancer and potential target for cancer therapy." (PMID 31956358, 2020). "A recent study showed a signature involving P4HA1, PLOD1, KDM3A, PLOD2, and ASPH predicted prognosis in various cancers including LUAD using bioinformatic analysis." (PMID 33299876, 2020). "Two KDM enzymes, KDM3A and KDM4B, which remove transcriptionally repressive H3K9me1/me2 and H3K9me2/me3 marks, respectively, have both been associated with oncogenic roles in numerous cancer types, suggesting that perturbation of their activity may be efficacious as a therapeutic option." (PMID 31390833, 2019). "Hypoxia is also an independent oncogenic driver and both KDM3A and KDM4B are co-activators of HIF-1α signalling in multiple cancer types." (PMID 31390833, 2019). "Subsequently, Kdm3a upregulates the expression of VEGF, adrenomedulin and GDF15 to promote cancer cell growth." (PMID 29156681, 2017). "A survey of enzymes related with H3K9 methylation indicated that KDM3A/JMJD1A, a demethylase for H3K9me1 and me2, gradually increases during cancer transformation and is elevated in patient tissues." (PMID 27034728, 2016). "Unlike miR-335, KDM3A is frequently upregulated in cancers and elevated KDM3A correlates with poor disease prognosis." (PMID 33888871, 2022). "Furthermore, the expression levels of KDM3A positively correlate with β-catenin target genes in CRC specimens from TCGA data and predictive of worse cancer outcomes." (PMID 32354028, 2020). "KDM3A, a H3K9 demethylase, is known to play an oncogenic role in human cancers including HCC." (PMID 33520978, 2020). "Clinical studies found that the demethylases of H3K9me2 and me3, such as lysine (K)-specific demethylase 3A (KDM3A, also known as JMJD1A or JHDM2A) and lysine (K)-specific demethylase 4A/B/C (KDM4A/B/C), are highly expressed in cancer tissues and regulate tumorigenesis." (PMID 30867030, 2019). "Unlike other cancers, knockdown of KDM3A does not affect HOXA1 expression or cell cycle distribution in MM cells." (PMID 26728187, 2016). "Clinical studies from different groups found that the demethylases of H3K9me2 and me3, such as lysine (K)-specific demethylase 3A (KDM3A, also known as JMJD1A or JHDM2A) and lysine (K)-specific demethylase 4A/B/C (KDM4A/B/C), are highly expressed in cancer tissues and regulate tumorigenesis." (PMID 27034728, 2016). "Overexpression of KDM3A, not surprisingly, has been correlated with aggravation of cancers." (PMID 35590288, 2022). "Coupled with the finding that KDM4B also regulates KDM3A expression and that KDM3A regulates both KDM4B and FOXA1 deposition at ER cis-regulatory sites, our data suggests a potential co-regulatory relationship between all three proteins to facilitate a cancer phenotype in ER-positive BC." (PMID 31390833, 2019). "An online database analysis (TIMER 2.0) shows the differential expression patterns of KDM3A and KDM3B (KDM3C not available) in various cancers and adjacent normal tissues across all TCGA tumors, highlighting their importance in tumorigenesis." (PMID 38926399, 2024). "Additionally, several studies suggested that both KDM3A and KDM6B were putative therapeutic targets in different cancer models, not including ESCC." (PMID 33318475, 2020).
cardiovascular disease (4 papers, 2022). "In recent years, epigenetic modulations were considered to be a crucial factor in the pathogenesis of cardiovascular diseases, and the functions of KDM3A have been explored." (PMID 36092165, 2022). "Connecting these data with current findings, such cardiac-influenced consequences further expand the biochemical actions of KDM3A across cardiovascular disease, albeit with divergent results between pathological cardiac hypertrophy and MIRI." (PMID 35338235, 2022). "As a member of the JMJC domain-containing proteins that belong to the histone demethylases family, KDM3A is deemed a key regulator in cardiovascular disease." (PMID 35571189, 2022). "However, as a crucial mediator in cardiovascular diseases, expressions of KDM3A and its downstream target (p-Akt) were downregulated after H/R treatment." (PMID 36092165, 2022). "Therefore, KDM3A is pivotal in the regulatory network of cardiovascular diseases." (PMID 36092165, 2022).
infection (4 papers, 2013 to 2026). The state of being infected such as from the introduction of a foreign agent such as serum, vaccine, antigenic substance or organism. "However, these outcomes were markedly ameliorated after AdKDM3A infection but were further exacerbated in KDM3A-knockout cardiomyocytes." (PMID 35338235, 2022). "In addition, LANA has been shown to interact with a number of host epigenetic factors (e.g. KAP1, mSin3, DNMT3a, KDM3A, Tip60, and hSET1), which may also be involved in the timing of PRC2 recruitment to the viral episome during de novo infection." (PMID 27606464, 2016). "KDM3A may still have an impact on the immune system in other contexts not explored in this study including infection, for example." (PMID 24312603, 2013).
adenocarcinoma (2 papers, 2018 to 2019). A common cancer characterized by the presence of malignant glandular cells. "To test if antagonizing an H3K9me1/2 KDM might impair TPC phenotypes and improve outcome, we depleted Kdm3a in CK1750 mouse adenocarcinoma cells." (PMID 30455465, 2018).
heart diseases (1 paper, 2018). "KDM3A is upregulated in human HCM and our data showed that JIB-04 is effective in inhibition of KDM3A in human heart cells, suggesting that JIB-04 may be a useful therapeutic agent in combating human heart diseases." (PMID 30531796, 2018).
neurological diseases (1 paper, 2023). "Among the top 50 database-predicted targeted genes, 8 genes (HOMER1, FRAT2, GRM5, TGFBR1, KDM3A, RGS2, ARRB1, and YWHAZ) were reported to be associated with axonal/neuronal regeneration/or neurological diseases." (PMID 36959678, 2023).
KDM3A also shares sentences with these, for which no sentence is quoted: hyperlipidemia (5 papers); metabolic disorders (3); metabolic syndrome (3); multiple myeloma (3); colorectal tumors (2); gastrointestinal tumor (2); liver (2); seminoma (2); Alzheimer disease (1); bone tumor (1); clear cell renal cell carcinoma (1); colorectal adenocarcinoma (1); depression (1); diabetic cardiomyopathy (1); encephalomyelitis (1); endothelial dysfunction (1); epidermoid carcinomas (1); Fanconi anemia (1); fatty liver (1); fibrosis (1); Glucose intolerance (1); Hypercholesterolemia (1); hypertrophic cardiomyopathy (1); hypertrophy (1); hypoxia (1); IgA vasculitis (1); intervertebral disc degeneration (1); monoclonal gammopathy of undetermined significance (1); nasopharyngeal carcinoma (1); oropharyngeal cancer (1).
A further 13 diseases each share a sentence with KDM3A in 1 paper.